IL10 (interleukin 10)
Diseases named in the same sentence as IL10 in open-access papers (continued):
Sharing a sentence is not in itself a finding about the gene and the disease.
colitis (continued). "On the other hand, it is known that the dysfunction of the intestinal barrier is an early event in the natural history of colitis in IL-10 deficient mice, although the mechanisms involved in such disturbance and the relation with dysbiosis or inflammation are still poorly understood." (PMID 36699599, 2022). "This has been further demonstrated by a study in which both FOXP3+ Tregs and Tr1 cells control Th17-mediated colitis in an IL-10-dependent manner as pathogenic Th17 cells expressing a dominant negative form of the IL-10 receptor were unresponsive to IL-10-mediated suppression." (PMID 36389662, 2022). "Although antibiotic treatment provides an attractive candidate for the treatment of colitis in patients with IL-10 deficiency, a recent study in IL-10-deficient animals demonstrated that intermittent antibiotic exposure accelerated the development of severe colitis in male mice." (PMID 36012618, 2022). "coli-induced colitis in IL-2−/− mice, while IL-10−/− mice mono-associated with pig isolates of B." (PMID 36376984, 2022). "As a potent regenerative agent, the R-spondin 1 protein (Rspo1) has been reported to promote repopulation of the mouse intestinal epithelium, resulting in the amelioration of inflammatory symptoms in not only DSS-induced experimental mice but also IL-10-deficient colitis model mice." (PMID 34835369, 2021). "Indeed, IL-4 deficiency can prevent the development of colitis in IL-10 knock out mice, which spontaneously develop colitis." (PMID 34737752, 2021). "Colitis-associated liver inflammation and fibrosis was less severe in IL-10 knockout IL-37tg mice." (PMID 33746950, 2021). "The IL-10-/- KO mice have been shown to be particularly susceptible to developing colitis." (PMID 34724858, 2021). "In IL-10−/− mice, loss of regulatory IL-10 secretion results in intolerance to their intestinal microbiota, unbalanced pro-inflammatory responses contributing to mucosal barrier disruption, and the development of spontaneous colitis." (PMID 34513862, 2021). "To gain a deeper insight into the mechanism underlying the effect of GSK-J4 in IL-10 production by T-cells upon DSS-induced colitis, we performed similar experiments but analysed the functional phenotypes of T-cells at an earlier time-point (day eight post-induction)." (PMID 33446666, 2021). "In Il-10 deficient mice, a high milk fat diet accelerated the onset of colitis promoting taurine conjugation of bile acids, greater availability of luminal sulphur and subsequent expansion of a specific sulphite-reducing opportunistic pathogen, Bilophila wadsworthia." (PMID 33806061, 2021). "The major role of IL-10 in intestinal homeostasis was revealed by genetic intervention in mice, where it was shown that both IL-10 deficient and IL-10 receptor deficient mice develop spontaneous colitis." (PMID 34220850, 2021). "A prominent example is the Il10-deficient mouse model for spontaneous colitis." (PMID 34381785, 2021). "In addition, another study conducted on the IL-10 deficient mice colitis model suggested that the binding of TNF by TNFR1 and following Il1b upregulation is essential for the early defensive response within colonic epithelial cells." (PMID 34124086, 2021). "Likewise, IL-10-deficient colitis model is frequently used mouse colitis model that mimics human CD." (PMID 34062869, 2021). "Similarly, E. coli causes colitis in Il10−/− mice but colibactin is required for colon tumors to form." (PMID 33969420, 2021). "Similarly, Seregin and colleagues showed that deficiency in NLRP6 increases the susceptibility to colitis in Il10−/− mice." (PMID 34705319, 2021). "Finally, Cel has been shown to significantly ameliorate experimental colitis in either IL-10 deficient mice or dextran sodium sulphate-induced colitis mice." (PMID 34959287, 2021). "IL-10 regulates intestinal homeostasis, and its deficiency leads to spontaneous colitis in mice." (PMID 34650393, 2021). "Mice deficient in IL-10 spontaneously develop colitis resembling IBD." (PMID 34943999, 2021).
colitis (continued). "Importantly, ingested K. aerogenes reaches the gastrointestinal tract, and the ectopic gut colonization by this bacterium exacerbates intestinal inflammation in DSS‐induced colitis and Il10‐deficient mice." (PMID 34705319, 2021). "As with the obese IL-10fl/fl Foxp3-Cre+ mice, we were concerned that the phenotype we observed in the obese Blimp-1fl/fl Foxp3-Cre+ mice was due to colitis, as Blimp-1 expression in Tregs and local IL-10 production have been associated with suppressing intestinal inflammation." (PMID 33351782, 2021). "Humans with IL-10 or IL-10R mutations also suffer from severe colitis at early age." (PMID 33717186, 2021). "In line with this, Sema 6D-deficient mice showed exacerbated DSS-induced colitis, which was characterized by a more severe leukocyte infiltration, decreased expression of IL-10 by lamina propria cells, and increased production of pro-inflammatory cytokines in the same cells." (PMID 33807591, 2021). "Achromobacter pulmonis (A. pulmonis) isolated from CD mAT could translocate to mAT and exacerbate both DSS-induced and Il10 gene-deficient (Il10−/−) spontaneous colitis in mice." (PMID 34814945, 2021). "Also, CD1d deficiency has been shown to affect Il10 transcription in intestinal epithelium, which was linked to increased mortality in an oxazolone-induced murine colitis model." (PMID 34220850, 2021). "In various experimental in vivo models of IBD, such as in DSS and Trinitrobenzenesulfonic (TNBS) colitis rat models and in IL-10 deficient mice model, increased mast cell proliferation and degranulation has been shown to play a critical role in disease progression." (PMID 33801010, 2021). "In an in vivo IL-10-deficient mouse model, treatment with a pegylated leptin antagonist resulted in attenuation of the clinical colitis score, a reversal of colitis-associated pathogenesis suppression of systemic and mucosal inflammatory cytokine production, and an increase in mucosal Treg cells." (PMID 33334069, 2020). "Furthermore, these levels were significantly higher in IL-10 deficient mice on the 129S6/SvEv background as compared to IL-10 deficient mice on the C57BL/6 background demonstrating that aggressiveness of colitis is significantly impacted by background strain." (PMID 32133003, 2020). "In addition, in IL-10-deficient mice, which spontaneously develop colitis, L. reuteri was shown to attenuate colonic inflammation." (PMID 32751784, 2020). "Similarly, histidine supplementation improved colitis condition in an IL-10-deficient Crohn’s disease model." (PMID 32208434, 2020). "Additionally, IL-10-deficient mice exposed to Helicobacter hepaticus, rodentium, or typhlonious develop severe colitis." (PMID 33147801, 2020). "Rather, we found that the vitamin B12 deficient group exhibited the lowest severity of colitis, highest increase in anti-inflammatory cytokine IL-10 and significantly decreased tissue damage compared to both vitamin B12 sufficient and vitamin B12 supplemented treatment groups." (PMID 32582756, 2020). "Although it is clear that macrophages lacking IL-10 signaling lead to increased development of Th17 cells in severe colitis, the molecular mechanisms underlying the complex functions of IL-10 in cancer immune surveillance under inflammatory conditions still remain elusive." (PMID 32670290, 2020). "However, Il4-/-Il10-/- double deficient mice showed decreased colitis induction after DSS treatment indicating that IL4 alone is not sufficient to reduce chronic colitis severity." (PMID 33664727, 2020). "Thus, the increased Il10 expression in HIF-2α deficient animals should have a protective effect during colitis." (PMID 33202783, 2020). "Trpa1 and Trpv1 gene deletion decreased dextran sulfate sodium (DSS)-induced colitis severity, as well as Il10−/−-induced spontaneous colitis in Trpv1-deficient mice, whereas Trpv1-deficient mice exhibited more severe colitis in the dinitrobenzene sulfonic acid (DNBS)-induced model." (PMID 32764237, 2020).
colitis (continued). "IL-10-deficient mice developed spontaneous colitis and enteritis and patients with mutations in IL-10 or its receptor, IL-10R, showed increased susceptibility to IBD, while IL-10R signaling was shown to regulate Th17 polarization and T cell proliferation in infantile-onset IBD patients." (PMID 32403220, 2020). "The importance of this feedback loop is demonstrated by the finding that mice with a conditional deletion of IL-10 in macrophages are sensitised to endotoxic shock driven by the TLR4 agonist LPS while total loss of IL-10 function results in sensitisation to colitis in both mice and people." (PMID 32725155, 2020). "Moreover, in IL10-deficient mice which spontaneously develop colitis, colitis is mitigated by reducing small intestinal permeability upon treatment with the zonulin peptide inhibitor AT-1001." (PMID 32731480, 2020). "In conclusion, this study provides initial evidence that the systemic delivery of Bry‐1 ameliorates spontaneous colitis in Il‐10−/− mice, and this effect is associated with the attenuation of intestinal barrier injury and the abnormal intestinal mucosal immune response." (PMID 31251471, 2019). "E. faecalis causes colitis in Il10−/− mice according to a previous report, but a remaining question was whether E. faecium is causally involved in colitis." (PMID 31767028, 2019). "This may go either way, e.g., IL-10 deficient mice show less severe chronic bowel inflammation in germ-free (GF) conditions, while acute chemically-induced colitis is exacerbated in GF mice compared to mice with a normal microbiome." (PMID 30915065, 2019). "In addition to providing protection from the key proinflammatory cytokine TNF-α, IL-10 also regulates chronic intestinal inflammation, so colitis of high severity occurs when low IL-10 levels are associated with intestinal endoplasmic reticulum (ER) stress." (PMID 30915354, 2019). "Altogether, it can be suggested that despite their normal differentiation, Maf-deficient RORγt− Treg are unable of preventing colitis due to their loss of function (decreased IL-10 production), combined to their low specificity to the gut microbiota in our experimental setting." (PMID 30992496, 2019). "Furthermore, the protective effects of AON treatment were examined in IL‐10‐deficient (IL‐10−/−) mice that can spontaneously develop colitis." (PMID 31559126, 2019). "In addition, F-I also promoted IL-10, a cytokine known to be protective in colitis because IL-10-deficient mice spontaneously develop enterocolitis and colon cancer." (PMID 31781511, 2019). "Deficiency of macrophages in IL-10−/− mice prevents the progression of colitis." (PMID 31886308, 2019). "Moreover, they reported the development of colitis in animals deficient in either interleukin-10, a cytokine exerting anti-inflammatory and regulatory functions, or Toll-like receptor 5, a receptor recognizing the bacterial flagellin." (PMID 31581570, 2019). "In accord with previous work, such blockade of IL-10 signaling resulted in typical features of colitis, including loss of weight/adiposity, splenomegaly, colomegaly, colon shortening, elevated MPO, increase in pathohistological scoring, and elevations in serum IL-6 and CXCL1." (PMID 31827095, 2019). "We tested whether HK2 deficiency in T cells would impair T cell-mediated inflammation by using a mouse model of colitis driven by IL-10 deficiency." (PMID 30140438, 2018). "Moreover, another study has shown that IgA-coated adherent-invasive Escherichia coli isolated from CD patients with spondyloarthritis can aggravate colitis or inflammatory arthritis after transplanted into interleukin-10 deficient or K/BxN mice." (PMID 30558634, 2018). "Most recently, in a model of IL-10-deficient mice, under housing conditions where no spontaneous colitis develops, administration of A. muciniphila to such SPF-reared mice or monocolonization of IL-10-deficient germfree mice with A. muciniphila resulted in colitis induction." (PMID 29766049, 2018).
colitis (continued). "Furthermore, IL-10 administration to IL-10-deficient murine models only protected from colitis if administered before disease establishment." (PMID 29545807, 2018). "Furthermore, genetic-linkage analysis of patients with colitis revealed distinct mutations in the IL-10 gene, demonstrating a central role for this cytokine in the negative feedback necessary to maintain mucosal homeostasis." (PMID 29760697, 2018). "In addition, the transfer of IL-33-induced, IL-10-producing regulatory B cells to IL-10-deficient mice reduced colitis severity and delayed disease onset." (PMID 29922293, 2018). "Moreover, dietary histidine ameliorates intestinal inflammation in the IL-10-deficient cell transfer model of colitis through the inhibition of NF-κB activation, following the down-regulation of pro-inflammatory cytokine production in macrophages." (PMID 30697218, 2018). "Failure to suppress uncontrolled CD4+ TH cell-mediated immune responses may lead to IBDs, as seen in mice lacking critical immunosuppression-associated genes, such as IL-10, which develop spontaneous colitis." (PMID 30697217, 2018). "Interestingly, IL-10-deficient mice rapidly developed colitis weeks after infection with MNV, which was associated with impaired epithelial barrier function and required the enteric microbiome." (PMID 29570694, 2018). "Thus, loss of Alpk1 function permits aberrant Th1 immunity that, in combination with IL-10 deficiency, causes aggressive and highly destructive colitis." (PMID 30228258, 2018). "A less esoteric setting of NLRP3 hyperactivity is colitis occurring in the presence of IL-10 deficiency which is due to the fact that IL-10 has the unique ability among commonly produced cytokines to inhibit the NLRP3 inflammasome and thus to cause hyperactivity of this inflammasome in its absence." (PMID 30455704, 2018). "In view of these findings one might ask why IL-10-deficient mice with secondary increases in NLRP3 deficiency not develop increased regulatory cell activity that prevents colitis." (PMID 30455704, 2018). "Interestingly, under germ-free condition il10−/− mice develop reduced colitis, and this is associated with reduced AOM-induced CRC development." (PMID 28632155, 2017). "Indeed, ‘regulatory’ Th17 cells have been demonstrated to efficiently hydrolyze ATP in a CD39-dependent manner, and CD39 deficiency reduced Th17 cell IL-10 production and increased pathogenic function in colitis." (PMID 28288184, 2017). "Inactivating mutations in IL-10 or the IL-10 receptor promote severe early-onset colitis." (PMID 27795299, 2017). "Nonetheless, this IL-10-encoding DNA plasmid pValac has been cloned into several L. lactis strains and was consistently able to diminish intestinal inflammation in a chemically induced murine model for colitis." (PMID 29387056, 2017). "However, C. jejuni strains from GBS patients induced mild colitis in C57BL/6 IL-10−/− mice associated with blunted type 1/17 but enhanced type 2 responses." (PMID 28789710, 2017). "Moreover, murine models deficient of the anti-inflammatory cytokine IL10 develop pronounced colitis, are predisposed to inflammation associated colorectal cancer, and display overexpression of TGFβ1." (PMID 27270652, 2017). "Of note, in the spontaneous colitis developed by IL-10-deficient mice, it seems that other mechanisms may also play a role since oral administration of Hsp65-LL still had some protective effect." (PMID 28194152, 2017). "When IL-10 deficiency is restricted to the Treg cell compartment, mice develop colitis." (PMID 28316998, 2017). "Finally, in mice deficient in IL-10 and the antimicrobial peptide Lipocalin-2, Alistipes was shown to flourish and was sufficient to induce colitis and tumorigenesis in IL-10 deficient mice." (PMID 28713378, 2017). "Furthermore, IL-10 knockout and IL-2-deficient mice manifest differential levels of severity of colitis dependent on the types of taxa that colonize their gut." (PMID 28904997, 2017).